ADAM19 (ADAM metallopeptidase domain 19)
Diseases named in the same sentence as ADAM19 in open-access papers (continued):
Sharing a sentence is not in itself a finding about the gene and the disease.
prostate carcinoma (1 paper, 2016). A carcinoma that arises from epithelial cells of the prostate gland. "Results from the clinical cohorts demonstrated that high levels of ADAM19 in microarrays are positively associated with lower stage (p = 0.02591) and reduced relapse (p = 0.00277) of human prostate cancer." (PMID 26912236, 2016). "It will be of interest to assess if there are any polymorphisms that reduce human ADAM19 expression, particularly in the prostate cancer environment." (PMID 26912236, 2016). "An exciting avenue for future investigation is the study of single nucleotide polymorphisms (SNPs) within ADAM19 in human prostate cancer." (PMID 26912236, 2016). "In the TCGA cohort we found that high ADAM19 expression in prostate cancer tissue was significantly negatively associated with tumour stage (cor = -0.18, p < 0.026)." (PMID 26912236, 2016). "Our examination of microarray data from two independent human prostate cancer cohorts indicated that high ADAM19 expression was associated with almost a six-fold increase in disease free survival and a significantly lower tumour stage." (PMID 26912236, 2016). "Our clinical data from two different cohorts provides compelling results for involvement of ADAM19 in prostate cancer and our in vitro data shows that ADAM19 can regulate prostate cancer cell growth and migration." (PMID 26912236, 2016). "We found that ADAM19 is a tumor suppressor in human prostate cancer patients and that it inhibits prostate cancer cell proliferation and migration in cell culture." (PMID 26912236, 2016). "In order to evaluate the relationship between ADAM19 levels and prostate cancer, we studied ADAM19 expression in publicly available microarray data from two distinct cohorts of prostate cancer patients." (PMID 26912236, 2016). "We found that ADAM19 expression is reduced in human prostate cancer cells compared to normal prostate epithelial cells." (PMID 26912236, 2016). "Using human normal and prostate cancer biopsies, we show that ADAM19 protein levels are elevated in normal prostate and reduced in prostate cancer specimens." (PMID 26912236, 2016). "Taken together, our immunohistochemical and microarray results and cellular studies have shown for the first time that ADAM19 is a protective factor for human prostate cancer." (PMID 26912236, 2016). "Immunohistochemical studies highlighted that ADAM19 protein levels were elevated in normal prostate tissue compared to prostate cancer biopsies." (PMID 26912236, 2016). "Human prostate tumour biopsies and normal prostate tissue samples on a Prostate Cancer Tissue Array were immunostained for ADAM19." (PMID 26912236, 2016). "Although our study suggests that ADAM19 is a tumour suppressor in prostate cancer, the mechanism is still to be elucidated." (PMID 26912236, 2016). "We then aimed to ascertain the direct effects of ADAM19 over-expression on human prostate cancer cell proliferation." (PMID 26912236, 2016). "Collectively, these findings suggest that ADAM19 is a beneficial factor in prostate cancer and functions by decreasing proliferation and migration." (PMID 26912236, 2016). "Intriguingly, human ADAM19 expression is reduced as the severity of prostate cancer rises which is a novel finding." (PMID 26912236, 2016). "Our group sought to investigate the role of ADAM19 in human prostate cancer." (PMID 26912236, 2016). "Excitingly, neutralisation of the activity of α4β1 and α5β1 by ADAM19 may be a mechanism by which this metalloproteinase reduces the progression of prostate cancer." (PMID 26912236, 2016). "The cleavage of Neuregulin 1-β1 by ADAM19 may therefore signify a possible anti-tumourigenic mechanism in human prostate cancer." (PMID 26912236, 2016). "Based on the emerging evidence of ADAM involvement in human cancer, we were interested to investigate if ADAM19 might play a role in prostate cancer using a combination of clinical cohorts and in vitro analyses." (PMID 26912236, 2016).
prostate carcinoma (continued). "We have shown for the first time that ADAM19 may serve as a tumor suppressor in human prostate cancer." (PMID 26912236, 2016). "The 80 and 45 kD bands were observed at considerably higher levels in RWPE-1 cells, consistent with the notion that ADAM19 may act as a tumor suppressor in prostate cancer cells." (PMID 26912236, 2016). "Our study provides evidence that elevated ADAM19 expression may serve as a tumor suppressor in human prostate cancer." (PMID 26912236, 2016). "Thus, although ADAM19 appears to be involved in driving other cancers, it appears to have the opposite effect in human prostate cancer." (PMID 26912236, 2016). "It is interesting to speculate regarding the post-translational modifications that may be at play in prostate cancer and may contribute to the reduced ADAM19 expression in prostate cancer." (PMID 26912236, 2016). "Further studies should aim to assess whether the ADAM19 gene is hypermethylated and silenced in prostate cancer." (PMID 26912236, 2016). "ADAM19’s ability to increase secretion of CRIP-2 may represent another possible anti-tumourigenic mechanism for ADAM19 in prostate cancer." (PMID 26912236, 2016). "Lastly, we examined the impact of ADAM19 over-expression on human prostate cancer cell migration." (PMID 26912236, 2016). "Interestingly, we have also shown that over-expression of ADAM19 in PC3 human prostate carcinoma cells inhibits migration of these cells." (PMID 26912236, 2016). "ADAM19 mRNA and protein levels were assessed in well characterised human prostate cancer cohorts." (PMID 26912236, 2016). "Further, this study suggests that upregulation of ADAM19 expression could be of therapeutic potential in human prostate cancer." (PMID 26912236, 2016). "Intriguingly, it would appear that the effects of ADAM19 may be limited to prostate cancer cells with reduced expression of ADAM19." (PMID 26912236, 2016). "ADAM19 expression was assessed in normal prostate epithelial cells (RWPE-1) and prostate cancer cells (LNCaP, PC3) using western blotting and immunocytochemistry." (PMID 26912236, 2016). "Our data indicates that ADAM19 induces TNF-α shedding in HEK293 cells, and further studies are required to elucidate the effect of TNF-α shedding by ADAM19 and it’s role in human prostate cancer." (PMID 26912236, 2016). "As PC3 prostate cancer cells are known to express TNF-α at the mRNA level, we also aimed to assess whether over-expression of ADAM19 in these cells may promote shedding of endogenous TNF-α." (PMID 26912236, 2016). "We are aware from our current study, that ADAM19 appears not to be shedding endogenous TNF-α from PC3 prostate cancer cells." (PMID 26912236, 2016).
psychosis (1 paper, 2012). "In BA9 we found a positive correlation between ADAM19 levels and the BISS psychosis factor (r = 0.595 p = 0.019)." (PMID 22590542, 2012).
pulmonary embolism (1 paper, 2023). The obstruction of the pulmonary artery or one of its branches by an embolus, sometimes associated with infarction of the lung. "As an example, we found one individual with pulmonary embolism while having a knockout of the essential gene ADAM19—a gene reported for its involvement in pulmonary disease." (PMID 37386248, 2023).
Sepsis (1 paper, 2015). Sepsis is defined as life-threatening organ dysfunction caused by a dysregulated host response to infection. "Sepsis induced the expression of three members of the disintegrin and metalloproteinase (ADAM) family, ADAM17, ADAM19 and ADAM10, and compstatin treatment mitigated the enhancement of these genes." (PMID 26337158, 2015).
septal defects (1 paper, 2006). "ADAM genes identified in this study have previously been associated with ventricular septal defects and valvular defects (ADAM19), fibrotic eye disease (ADAMTS9), disrupting angiogenesis (ADAMTS8), and cell adhesion (ADAM 28)." (PMID 16948840, 2006).
serous ovarian cancer (1 paper, 2014). "Similarly ARID3B overexpressing cells exhibited increased expression of genes (ST3GAL6, ADAM19, and HTATIP2) reported to be part of the serous ovarian cancer ascites CSC signature." (PMID 25327563, 2014).
Stroke (1 paper, 2023). Sudden impairment of blood flow to a part of the brain due to occlusion or rupture of an artery to the brain. "A locus in ADAM23 has been shown to correlate with stroke outcome, and in our study multiple ADAM gene family members such as ADAM9, ADAM17, ADAM19 were associated with poor stroke outcomes." (PMID 36691064, 2023).
systemic sclerosis (1 paper, 2024). A chronic disorder, possibly autoimmune, marked by excessive production of collagen which results in hardening and thickening of body tissues. "ADAM19 (ADAM Metallopeptidase Domain 19) is known to be involved in extracellular matrix (ECM) remodeling, yet its specific function in systemic sclerosis (SSc) fibrosis remains unclear." (PMID 39716051, 2024).
triple-negative breast carcinoma (1 paper, 2020). An invasive breast carcinoma which is negative for expression of estrogen receptor (ER), progesterone receptor (PR), and human epidermal growth factor receptor 2 (HER2). "While changes such as the upregulation of ADAM19 in the invading subpopulation may be shared among the triple negative breast cancer cells tested in this study, other genes, such as BEX1 and CDH13, were seen in some samples but not in others." (PMID 32238832, 2020).
type 2 diabetes (1 paper, 2018). "Notably, several age-downregulated genes, such as Plxdc2, Igf1, Igf2bp3, and Igf1r, and upregulated genes, such as Adam19 and Tmem163, have been linked to IGF signaling or type 2 diabetes." (PMID 30180872, 2018).
Ventricular arrhythmia (1 paper, 2025). "Notably, overexpression of Adam19 did not abolish the left ventricle (LV) functional benefit of LIPUS, and overexpression of Adam19 did not abolish the LV functional benefit of LIPUS on ventricular hypertrophy, fibrosis, cardiac function, and ventricular arrhythmia (VA) inducibility." (PMID 41063651, 2025).
tumor (32 papers, 2012 to 2025). "In this list, we highlighted MYO10 and ADAM19, two genes linked to tumor aggressiveness." (PMID 30814494, 2019). "Particularly, ADAM19 has been reported to play pro-tumor or anti-tumor roles, depending on the cancer type." (PMID 37835389, 2023). "METTL14 performed tumor suppressor functions similar to that of METTL3 in the development of GSCs by targeting mRNA levels of ADAM19, EPHA3 and KLF4." (PMID 34521394, 2021). "More important, there were elevated expression levels of ADAM10, ADAM17, and ADAM19 in tumor tissues as they became more malignant in terms of pathological grading." (PMID 33043016, 2020). "Mettl3 normally methylates ADAM19 mRNA, resulting in the degradation of ADAM19 required for tumor suppression." (PMID 31798620, 2019). "Of interest, further experiments demonstrated that inhibition of ADAM19 by miR-30c partially mediated the anti-tumor effect of miR-30c." (PMID 25799050, 2015). "IER3 dependent tumor suppressor pathway in NB cells relies on ADAM19 gene." (PMID 40090972, 2025). "The oncohistone, H2BE76K upregulated ADAM19, which in turn participated in enhanced tumor colony formation that could be inhibited by knock-down." (PMID 38331475, 2024). "The targeted inhibition of ADAM19 may be crucial for the treatment of certain types of tumours and inflammatory diseases." (PMID 36534664, 2022). "Tumor samples of Inserm series were predicted in 2 and 4 subtypes molecular classification using a predictor based on nine genes: ADAM19, ETS1, and PDCD1LG2 for C1 and C2; CLDN1, DSC3, and SLC24A3 for C1A and C1B; CHL1, ECM2, and PTPN13 for C2A and C2B subtype prediction." (PMID 32083805, 2020). "ADAM19 has been positively associated with numerous diseases, but has not been shown to be a tumor suppressor in the pathogenesis of any human cancers." (PMID 26912236, 2016). "Consitently, ADAM19 was upregulated in tumor tissues detected by western blot." (PMID 25799050, 2015). "Based on the expression profile of FPGT, ST3GAL6 and ADAM19 in SP gene signature list, we propose a probable mechanism, which may be active in the SP cells that accounts for the SP cell survival, differentiation and tumor maintenance in ovary." (PMID 22272227, 2012). "By contrast, expression of each of ADAMTS1, ADAM19, ADAMTS13, and ADAMTS17 in tumor tissue was 0.75-fold lower than that in NCL." (PMID 36230656, 2022). "The ADAM19, FLI1, and MSC genes were hypermethylated in tumor tissues in 59 (41.8%), 57 (40.4%), and 80 cases (56.7%), respectively." (PMID 31675985, 2019). "Based on these results and identification of these genes (FPGT, ST3GAL6 and ADAM19) in our SP gene list, we identified a potential mechanism, which may be active in the SP cells that accounts for the SP cell survival, differentiation and tumor maintenance in ovary." (PMID 22272227, 2012). "We subsequently examined ADAM10, ADAM17 and ADAM19 expression in the tumour cell and found that while ADAM10/17 are not induced by platelet cloaking, ADAM19 is potently induced." (PMID 30908480, 2019). "In spite of its established role as a TNF sheddase and its deregulation in tumour cell lines ADAM19 expression by Theileria-infected leukocytes has not yet been described." (PMID 25375322, 2014). "Thus, in this heterologous mouse model for Theileria-transformed macrophage dissemination ectopic expression of Flag-Δ169-c-Jun that diminishes MMP9/ADAM19 and increases TIMP3 expression led to ablation of tumour dissemination by the engineered attenuated line." (PMID 25375322, 2014).
cancer (25 papers, 2011 to 2024). A tumor composed of atypical neoplastic, often pleomorphic cells that invade other tissues. "ADAM19 encodes a metalloprotease that belongs to the ADAM family associated with cancer progression." (PMID 30814494, 2019). "In the GSE40272 cohort, there was a significant association between high median ADAM19 expression levels and reduced cancer relapse (Hazard Ratio 0.1749, p < 0.003)." (PMID 26912236, 2016). "Many of the up-regulated transcripts are associated with cancer biology; e.g., ADAM19 and CDH2." (PMID 21789255, 2011). "Induced Adam19 expression is frequently seen among different cancer cell lines and is therefore a bona fide target for the treatment of cancer." (PMID 29254206, 2017). "Two metalloproteinases, ADAM metallopeptidase domain 19 (ADAM19) and matrix metallopeptidase 9 (MMP9), upregulated under hypoxia, are also associated with cancer progression, mainly through modulation of cell adhesion and migration in several cancers, including NSCLC." (PMID 38674080, 2024). "Furthermore, we found the co-expression of immune activation genes and ADAM19, revealing a significant correlation of ADAM19 with immune activation genes among almost all 33 types of cancer." (PMID 37082201, 2023). "However, the functions of ADAM19 in cancers still remain to be elucidated." (PMID 26482227, 2015). "Thus, the genes LOXL3, ADAM19, FBN2, and RND3 are associated with cancer relevant biological processes such as loss of adhesion, proliferation, migration and metastasis and are therefore might be functionally related to CLIP2 in the context of radiation induced PTC-carcinogenesis of PTC." (PMID 32727620, 2020). "ADAM19, FPGT and ST3GAL6 were found to be over expressed in SP cells and may be potential cancer stem-like cell related genes." (PMID 22272227, 2012). "However, this study shows that ADAM19 is not the only target for miR-30c because the cancer development rate was greater than the reduction in ADAM19." (PMID 37185715, 2023).
infection (5 papers, 2011 to 2023). The state of being infected such as from the introduction of a foreign agent such as serum, vaccine, antigenic substance or organism. "Moreover, we indicated nDens of 2 genes induced and 2 genes repressed in all infection performed and nDens of all genes discussed above (IL-1β, IL-6, IL-12, TNF-α, IL-10, ADAM19, CCR7, CCL20 and IL-18)." (PMID 21436989, 2011). "We found that the levels of ADAM17, not ADAM15 or ADAM19, increased significantly upon infection." (PMID 30687645, 2018).
degenerative diseases (1 paper, 2021). "These include Spon2, Adam19, Arntl, Cdkn1a, Cry2, Per2, Per3, Wee1, Rcan1, Slc41a3, Errfi1, and Bhlhe41, which are related to numerous cardiovascular and degenerative diseases of other organs as well as varying aging processes." (PMID 33668521, 2021).
inflammation (1 paper, 2018). Aberrant reaction of the microcirculation characterized by movement of fluid and leukocytes from the blood into extravascular tissues. "IL4 and IL5RA are well-characterized cytokines responsible for Th2 cell differentiation and effector function, ADAM19 is involved in airway and vasculature remodeling, and PRG2 and EPX are both eosinophil-related proteins that play key roles in eosinophil-related airway inflammation." (PMID 29692868, 2018).
renal disease (1 paper, 2013). "ADAM19 (Meltrin-beta) is the upstream regulator for alpha-2-macrogulbulin (A2M) whose role in renal disease has been identified in several studies." (PMID 24339887, 2013).
ADAM19 also shares sentences with these, for which no sentence is quoted: lung adenocarcinoma (2 papers); acute myeloid leukemia (1); bladder cancer (1); blood cancers (1); brachydactyly (1); choriocarcinoma (1); colon adenocarcinoma (1); condyloma acuminatum (1); depression (1); endometrial carcinoma (1); esophageal squamous cell carcinoma (1); Fasciola infection (1); gouty arthritis (1); hepatocellular carcinoma (1); lymphoma (1); malaria (1); metastasis (1); myocardial infarction (1); osteoarthritis (1); parasite infection (1); prostate tumour (1); renal carcinoma (1); rheumatoid arthritis (1); squamous cell carcinoma (1); Ventricular hypertrophy (1).